SAMHD1 (SAM and HD domain containing deoxynucleoside triphosphate triphosphohydrolase 1)
Diseases named in the same sentence as SAMHD1 in open-access papers (continued):
Sharing a sentence is not in itself a finding about the gene and the disease.
HIV-1 infection (continued). "The IFNα-induced block to HIV-1 infection is observed in macrophages, PMA-treated and dividing THP-1 cells as well as in U87-MG cells, but not in U937 cells (; and this manuscript), suggesting that induction of SAMHD1 expression by IFNα does not directly correlate with a block to HIV-1 infection." (PMID 23442224, 2013).
Aicardi-Goutières syndrome (91 papers, 2010 to 2025). "Mutations in SAMHD1 are associated with Aicardi–Goutières syndrome, a rare genetic autoimmune disorder characterized by chronic brain inflammation and abnormal activation of the immune system, resulting in symptoms that resemble viral infections." (PMID 39655951, 2025). "Germline mutations in SAMHD1 are responsible for a rare, inheritable, auto-inflammatory disease, Aicardi–Goutières syndrome (AGS), characterized by the strong, unresolved activation of type I interferon (IFN) signaling." (PMID 40581121, 2025). "Homozygous mutations in the sterile alpha motif and HD domain-containing protein 1 (SAMHD1) gene are linked to Aicardi–Goutières syndrome (AGS), a rare inflammatory neurological disorder." (PMID 40352920, 2025). "Recessive inheritance of SAMHD1 missense variants and PTVs have been associated with Aicardi–Goutières syndrome, a congenital autoimmune disease." (PMID 39261734, 2024). "Mutations in SAMHD1 have been associated with autoimmune diseases such as Aicardi–Goutières syndrome (AGS), which are characterized by aberrant immune activation." (PMID 38888311, 2024). "One protein associated with Aicardi–Goutières syndrome, SAMHD1, has been shown to negatively regulate the IFN-1 signaling pathway." (PMID 35085552, 2022). "SAMHD1 deficiency also affects the brain, resulting in an inflammatory neurodegenerative disorder, Aicardi–Goutiéres syndrome (AGS)." (PMID 36072652, 2022). "Rare homozygous and compound heterozygous loss-of-function mutations in SAMHD1 result in an immune encephalopathy known as Aicardi Goutieres’ syndrome." (PMID 35023831, 2022). "Mutations in SAMHD1 are linked to the pathogenesis of chronic lymphocytic leukemia and Aicardi–Goutières syndrome (AGS)." (PMID 36362045, 2022). "Germline SAMHD1 mutations are implicated in Aicardi-Goutieres syndrome (AGS), an autosomal recessive condition that results in autoimmune inflammatory encephalopathy." (PMID 36199081, 2022). "Mutations in SAMHD1 cause Aicardi-Goutières syndrome (AGS), a monogenic lupus-like autoimmune disease." (PMID 33857133, 2021). "SAMHD1 mutations are associated with Aicardi–Goutières syndrome (AGS), a congenital neurodegenerative autoimmune disorder." (PMID 34696158, 2021). "The purine nucleotides are also accumulated in Aicardi–Goutières syndrome with germline SAMHD1 mutations." (PMID 34696158, 2021). "Germline loss-of-function mutations in the SAMHD1 gene cause Aicardi-Goutières syndrome, which is manifested by increased production of type I interferon (IFN-I)." (PMID 33177202, 2021). "SAMHD1 mutations were associated with cancer development and Aicardi-Goutières syndrome, a severe congenital inflammatory disease." (PMID 32630049, 2020). "Mutations in several genes can cause Aicardi–Goutières syndrome, including alterations in the SAMHD1 gene." (PMID 32384610, 2020). "To study the role of disease-causing mutations in SAMHD1 in vitro, we generated hiPSCs from a patient with Aicardi–Goutières syndrome (AGS)." (PMID 32384610, 2020). "Genetic mutations in SAMHD1 induce a rare inflammatory encephalopathy called Aicardi–Goutières syndrome (AGS), which phenotypically resembles viral infection." (PMID 32244340, 2020). "Homozygous mutations in SAMHD1 gene have been identified in 17% of patients with Aicardi-Goutières syndrome (AGS), an autoimmune disorder that is attributed to excessive accumulation of small DNA fragments in brain." (PMID 31547393, 2019). "Genetic autosomal recessive mutations in RNA processing enzymes of the RNASEH2 complex, ADAR1, and SAMHD1 cause abnormal induction of type-I IFNs and lead to Aicardi-Goutières syndrome (AGS) and related interferonopathies." (PMID 31354738, 2019). "SAMHD1 is responsible for the inhibition of a wide range of viruses and retroviruses in myeloid cells, and defects in SAMHD1 can cause Aicardi-Goutières Syndrome, an autoimmune disorder characterized by persistent immune activation." (PMID 30656243, 2018).
Aicardi-Goutières syndrome (continued). "SAMHD1 is mutated in cancer and in the neurodegenerative autoimmune disorder Aicardi–Goutières syndrome in which aberrant nucleic acids accumulate, inducing innate immunity." (PMID 30456372, 2018). "Polymorphisms in the SAMHD1 gene are associated with Aicardi-Goutières Syndrome (AGS), an early onset autoimmune inflammatory disease characterized by constitutive type I interferon (IFN) expression." (PMID 29515139, 2018). "From the largest cohort of 374 patients, intracerebral vasculitis was seen frequently enough to be confirmed as being associated with the Aicardi-Goutieres syndrome phenotype, especially in the patients with SAMHD1 mutations." (PMID 30560109, 2018). "Mutations in human SAMHD1 cause Aicardi-Goutières syndrome (AGS), a rare monogenic disorder resembling congenital virus infection and typified by early-onset brain disease." (PMID 27477283, 2016). "Mutations in SAMHD1 are associated with the Aicardi–Goutières syndrome, an autoimmune disorder exemplified by irregular type I IFN responses." (PMID 27411355, 2016). "Mutations in the SAMHD1 gene result in the Aicardi-Goutières syndrome (AGS), a genetic disorder caused by pathologic activation of interferon signaling." (PMID 27511536, 2016). "Loss of SAMHD1 has been linked to Aicardi-Goutières syndrome (AGS), an early-onset inflammatory disorder affecting particularly the brain." (PMID 27525044, 2016). "A previous linkage study of SAMHD1 with Aicardi-Goutières syndrome associated the gene with a human disease for the first time." (PMID 26504826, 2015). "SAMHD1 was known for the association of its mutations with the Aicardi-Goutieres syndrome (AGS), a congenital autoimmune disease." (PMID 26134849, 2015). "Mutations in SAMHD1 were later found to associate with the Aicardi-Goutieres syndrome (AGS), a congenital autoimmune disease that is characterized with low but persistent levels of type I interferon and inflammatory cytokines." (PMID 26134849, 2015). "Supporting this conclusion, the authors also demonstrated that a mutation in SAMHD1 in cells from a patient with Aicardi-Goutiere's syndrome renders resting CD4+ T cells permissive to HIV infection." (PMID 24404168, 2014). "It is noteworthy that the ability of cells from Aicardi-Goutières syndrome patients with SAMHD1 mutations to control HIV-1 is impaired." (PMID 24854580, 2014). "Polymorphisms in the gene encoding SAMHD1 are associated with Aicardi-Goutières Syndrome, a neurological disorder characterized by increased type-I interferon production." (PMID 24586870, 2014). "SAMHD1 is also one of the genes linked to Aicardi-Goutières syndrome, a hereditary autoinflammatory disease characterised by spontaneous and chronic production of type I interferons." (PMID 24854580, 2014). "In cells from healthy human donors, SAMHD1 appears to be localized exclusively to the nucleus, whereas in cells of Aicardi-Goutières syndrome (AGS) patients with mutations in SAMHD1 cytoplasmic accumulation of SAMHD1 has been observed." (PMID 24712655, 2014). "Mutations in SAMHD1 have been associated with Aicardi-Goutières syndrome (AGS) a condition presenting with increased type I interferon levels mimicking congenital viral infection." (PMID 24712655, 2014). "SAMHD1 mutations are involved in Aicardi-Goutières syndrome (AGS), a genetic encephalopathy mimicking congenital viral infection." (PMID 24523981, 2013). "SAMHD1 mutations can cause Aicardi-Goutières syndrome (AGS), which is characterized as an improper immune activation resulting from the accumulation of intracellular DNA." (PMID 24035396, 2013). "Mutations in the SAMHD1 gene have been implicated with Aicardi-Goutieres Syndrome (AGS), a disease that is associated with increased production of interferon-alpha and thus mimics congenital virus infections." (PMID 23092512, 2012).
Aicardi-Goutières syndrome (continued). "SAMHD1 gene mutations are associated with Aicardi-Goutières syndrome (AGS), an inherited autoimmune disease mimicking congenital viral infection with elevated type I interferon production." (PMID 23092163, 2012). "Several single nucleotide polymorphisms in the SAMHD1 gene have been associated with Aicardi-Goutières syndrome (AGS), a very rare and severe autoimmune disease." (PMID 22174685, 2011). "The SAMHD1 gene is mutated in a subset of patients suffering from Aicardi-Goutières syndrome (AGS), an early-onset disease that resembles a congenital viral infection." (PMID 22174685, 2011). "Furthermore, a SAMHD1 variant (∆120–123) from Aicardi-Goutières syndrome (AGS) patients was defective in HIV-1 Gag binding." (PMID 38888311, 2024). "Sterile alpha motif and HD domain-containing protein 1 (SAMHD1) was initially associated with Aicardi-Goutières Syndrome (AGS) and has been identified as a deoxyribonucleotide triphosphohydrolase (dNTPase) with a well-defined human immunodeficiency virus type one (HIV-1) restricting function." (PMID 36139652, 2022). "In addition, it is known that mutations in SAMHD1 are associated with the Aicardi–Goutières syndrome, and recent studies suggest roles of SAMHD1 in double-stranded break repair, genomic stability, and potentially some types of cancer." (PMID 33450175, 2021). "Furthermore, SAMHD1-deficient primary peripheral blood mononuclear cells isolated from patients with Aicardi-Goutières syndrome are also highly permissive to HIV-1 replication." (PMID 33177202, 2021). "However, the effect of SAMHD1 inactivating mutations on immune system diversification in patients with Aicardi–Goutières syndrome is yet to be analyzed." (PMID 34696158, 2021). "Germline mutations in the SAMHD1 gene have been associated with the Aicardi-Goutières syndrome (AGS), a hereditary autoimmune encephalopathy, suggesting that constant immune-stimulating IFN signaling in absence of SAMHD1 is the underlying basis for aberrant inflammation in AGS." (PMID 33591315, 2021). "However, SAMHD1 mutations produced in the Aicardi–Goutières syndrome are defective in LINE-1 inhibition." (PMID 27411355, 2016). "The gene encoding SAMHD1 is best known in the context of Aicardi-Goutières syndrome (AGS), a rare genetic disorder that causes encephalopathy and other sequelae that have striking resemblance to congenital infection and to some aspects of systemic lupus erythematosus." (PMID 21994799, 2011). "The finding that SAMHD1-KO in THP-1 cells triggers the type I IFN response implies that these cells recapitulate the phenotype observed in patients with Aicardi–Goutières syndrome (AGS)." (PMID 40581121, 2025). "SAMHD1 inhibits cGAS-STING and NF-κB, and LOF mutations cause Aicardi-Goutières Syndrome (AGS), an autosomal recessive monogenic type I interferonopathy." (PMID 40894167, 2025). "In humans, mutations in sterile α motif and histidine-aspartate domain–containing protein 1 (SAMHD1) lead to the development of a type I interferonopathy known as Aicardi–Goutières syndrome (AGS)." (PMID 40581121, 2025). "A series of mutations in human sterile alpha motif (SAM) domain and histidine–aspartate (HD) domain–containing protein 1 (SAMHD1) gene were identified in Aicardi–Goutières syndrome (AGS)." (PMID 37567474, 2023). "While Aicardi Goutieres’ syndrome is a severe recessive genetic disorder, case reports of SAMHD1-related disease often describe heterozygous parents and siblings as being unaffected or with milder disease (familial chilblain lupus 2)." (PMID 35023831, 2022). "They contribute to pathological cell motility, enhancing neointima formation after vascular injury (ACTR2), cerebral vasculopathy in Aicardi–Goutieres syndrome (SAMHD1) and cells’ activation, senescence and apoptosis (TERF2IP)." (PMID 36614026, 2022).
Aicardi-Goutières syndrome (continued). "Mutations in TREX1 (three prime repair exonuclease 1) or SAMHD1 (SAM domain and HD domain-containing protein 1), for instance, lead to the same autoimmune disease, Aicardi-Goutières syndrome (AGS)." (PMID 35058771, 2021). "Mutations in the SAMHD1 gene are associated with an autoimmune disorder through the irregular response of type I IFN, which characterizes Aicardi-Goutières syndrome, in which there is marked production of IL-12 and TNF-α." (PMID 32656092, 2020). "Aicardi–Goutières syndrome is an inflammatory disease that occurs due to mutations in any of the TREX1, RNASEH2A, RNASEH2B, RNASEH2C, SAMHD1, ADAR, or IFIH1 genes." (PMID 30560109, 2018). "TREX1, SAMHD1 and ADAR1 are known LINE‐1 repressors and when mutated cause the autoinflammatory disorder Aicardi‐Goutières syndrome (AGS)." (PMID 29959219, 2018). "SAMHD1 also protects the cells against autoimmune responses, such as the Aicardi-Goutieres syndrome." (PMID 24810600, 2014). "In addition, Jafarpour described a de novo mutation in RNASEH2A, which is one of the genes, along with SAMHD1 (case 12) and RNASEH2B (sibling of case 13) that can cause Aicardi-Goutières Syndrome (AGS), a type 1 interferonopathy, autoinflammatory disorder." (PMID 40894167, 2025). "Furthermore, several factors at the interface with HIV are also involved in major cellular dysfunctions, such as the HIV restriction factor SAMHD1 also involved in Aicardi–Goutières syndrome (AGS)." (PMID 38959200, 2024). "Certainly in the autoimmune vasculitis variants known as Aicardi-Goutières syndrome, where altered degradation of cytosolic DNA or RNA is caused by mutations in TREX1/SAMHD1/RNASEH2A/B/C/ADAR/IFIH1/PNPT1, the progressive immune activation leads to phenotypes of neuro-inflammation/-degeneration." (PMID 34345994, 2021). "Aicardi-Goutieres syndrome (AGS) is an early-onset encephalopathy that can be caused by a gene mutation in one of 7 discovered genes so far (TREX1, RNASEH2B, RNASEH2C, RNASEH2A, SAMHD1, ADAR1, and IFIH1)." (PMID 32737687, 2020). "The most prominent examples are mutations in Three-prime Repair Exonuclease 1 (TREX1) or Sam domain and HD domain 1 (SAMHD1), that are associated with the rare autoinflammatory disease Aicardi-Goutieres syndrome (AGS) characterized by an exaggerated type I IFN response." (PMID 29487579, 2018). "The genetic dissection of a particular type I interferonopathy, Aicardi-Goutières syndrome, initially described as an early-onset progressive brain disease, identified mutations of the TREX1, RNASEH2A, RNASEH2B, RNASEH2C, SAMHD1, ADAR, and MDA5 genes as causal." (PMID 27190218, 2016). "The SAMHD1 gene was originally identified from a human dendritic cell cDNA library as an ortholog of the mouse IFN-γ-induced gene Mg11 and was recently linked to a rare genetic condition, Aicardi-Goutières syndrome." (PMID 26504826, 2015). "The lack of SAMHD1 protein expression in humans due to SAMHD1 gene mutations can result in a rare, but severe autoimmune disease called Aicardi-Goutieres syndrome (AGS)." (PMID 24257155, 2013). "The function of SAMHD1 was not clear, until it was found that this gene mutation caused Aicardi-Goutieres syndrome (AGS)." (PMID 23254112, 2012). "Although the biological function of SAMHD1 is not very clear, mutations in SAMHD1 have been associated with Aicardi-Goutieres syndrome (AGS), a genetic encephalopathy with symptoms mimicking viral infection." (PMID 23336082, 2012). "In addition, SAM domain and HD domain containing protein 1 (SAMHD1), involved in Aicardi–Goutières syndrome (AGS) as an improper immune activation, is an antiviral factor that inhibits human immunodeficiency virus type 1 (HIV-1) and herpes simplex virus 1 (HSV-1)." (PMID 37509063, 2023).
Aicardi-Goutières syndrome (continued). "Discoveries that SAMHD1 mutations cause Aicardi-Goutières syndrome (AGS) and that SAMHD1 restricts HIV-1 replication in non-cycling immune cells established the role of SAMHD1 as an innate immunity factor involved in interferon signaling and retroviral restriction." (PMID 30044979, 2018). "Aicardi-Goutieres syndrome is classified as a monogenic interferon disease resulting from an aberrant mechanism involving intracellular nucleic acid sensing mediated by TREX1, RNASEH2A, RNASEH2B, RNASEH2C, SAMHD1, ADAR1 or IFIH1." (PMID 39286150, 2024). "TREX1, SAMHD1 and ADAR1 are all negative modulators of LINE-1 and when mutated cause the autoinflammatory disorder Aicardi–Goutières syndrome (AGS)." (PMID 32244340, 2020). "In addition, SAMHD1 knock-down in RAW264.7 cells induced the production of type-I interferon and several interferon-stimulated genes, modeling the situation in Aicardi-Goutières Syndrome." (PMID 24586870, 2014). "In the absence of SAMHD1, constitutive activation of the cGAS/STING pathway ensues, providing an explanation as to why mutations in this locus is linked to the development of various cancers and the autoimmune disease Aicardi-Goutières Syndrome." (PMID 33563288, 2021).